VHL (von Hippel-Lindau tumor suppressor)
Diseases named in the same sentence as VHL in open-access papers (continued):
Sharing a sentence is not in itself a finding about the gene and the disease.
tumor (continued). "Interestingly, no CCC nor CRC-UMF lacking a VHL mutation were found in the blood of the 25 patients with a VHL-mutated tumor." (PMID 29732003, 2018). "Finally, as controls, we analyzed the mRNA expression of two hypoxia-inducible genes, VEGFA and CA9, and observed increased expression in the VHL-deficient tumor samples as expected." (PMID 29435132, 2018). "Additionally, mutation or silencing of tumor suppressive genes such as VHL and PTEN, accompanied by the activation of oncogenes sometimes, contributes to the carcinogenesis of ccRCC." (PMID 29357836, 2018). "Taken together, the results in four NCI60 cell lines and in TCGA tumours support the hypothesis that VHL inactivation is associated with global genome hypermethylation." (PMID 30006568, 2018). "Hypoxia inducible factors in RCC are upregulated due to VHL mutation but also due to tumor hypoxia." (PMID 30123419, 2018). "Furthermore, loss of 3p has been seen in a number of other human cancers and our findings of 3p loss in ELST further support the presence of one or more tumor suppressor genes including VHL in this region of the chromosome." (PMID 30340515, 2018). "One of the reasons that this could be such an interesting preventative opportunity is that the region of 3p loss invariably encompasses all four tumor suppressor genes of VHL, PBRM1, BAP1, and SETD2, and hence spans at least 40 Mb." (PMID 29656891, 2018). "Thus, among the 161 single cells found with the same VHL mutation detected in the tumor tissue, 57 (35%) have been identified as CCC by cytopathological analysis and 104 (72%) have been identified as cancer cells by genetic analysis." (PMID 30177639, 2018). "PD-L1 is a novel transcription target of HIF2α and HIF1α in tumor cell deficient in VHL." (PMID 29535842, 2018). "The right-sided K097 tumor harbored a VHL mutation and VHL was methylated in the left tumor." (PMID 29656894, 2018). "Interestingly, three patients (10%) harboured two simultaneous VHL mutations in their primary tumor sample, each located on a different exon of the VHL gene." (PMID 29732003, 2018). "Furthermore, our data show that the cytopathological diagnosis of CRC-UMF also matches, in a large proportion of cells (85.1%), with the presence of the same VHL mutation found in the tumor tissue, thereby strongly suggesting their tumor cell nature." (PMID 29732003, 2018). "Patient with catecholamine-secreting tumours due to RET and NF1 mutations secrete high levels of metanephrine, indicating epinephrine production in the tumour, while patients with mutations in the VHL gene exhibited an increased production of normetanephrine, indicating norepinephrine production." (PMID 29166454, 2017). "The presence of VHL mutation in tumor cells has been shown to carry a survival benefit for patients with CC-RCC, which could explain the less aggressive nature of the tumors with overexpressed adipophilin (and our study)." (PMID 28404922, 2017). "PBRM1, SETD2 and BAP1, similarly to VHL, map to the 3p21 and this suggests that essential component of ccRCC pathogenesis may be allelic loss of 3p resulting in haploinsufficiency for four tumor suppressors simultaneously." (PMID 28212566, 2017). "By bioinformatic analyses, the authors strengthened the hypothesis that a loss of VHL is associated with enhanced miR-28-5p expression and chromosomal instability, resulting in tumor progression in clear cell RCC." (PMID 29165391, 2017). "Alternatively, VHL partial deficiency may activate HIF-independent pathways which may be relevant to its tumour suppressor function." (PMID 28036268, 2017). "The human von Hippel-Lindau (VHL) tumor suppressor gene encodes three different protein isoforms." (PMID 29100286, 2017). "It has previously been described only as a VHL-associated tumour." (PMID 28261513, 2017). "We next investigated whether aRTL was correlated to the onset age of VHL‐associated tumors in tumor‐affected patients." (PMID 28776935, 2017).
tumor (continued). "For example, one patient-specific factor which could influence tumour development is which germline VHL mutation is found in the patient." (PMID 27174753, 2016). "Minor populations of tumor cells with VHL mutations are extremely rare." (PMID 27530247, 2016). "Our findings indicate that loss of VHL could be driving tumour cell dissemination through stabilization of HIF-1α in RCC." (PMID 27358011, 2016). "To investigate whether increased Dicer expression affects tumor growth of VHL-deficient ccRCC in vivo, we subcutaneously implanted immunocompromised nude mice with 786-O cells stably expressing either ectopic Dicer or empty vector." (PMID 26943772, 2016). "Therefore, distinct 3p LOH, combined with contingent driver gene mutations and independent VHL hypermethylation, led to independent tumor origin and parallel evolution of bilateral ccRCC in these two patients." (PMID 27383411, 2016). "HIF1α stabilization due to loss of VHL decreased tumor growth." (PMID 26841847, 2016). "It is tempting to speculate that the response rate of ccRCC patients may be linked to the VHL mutation type present in a tumor." (PMID 27530247, 2016). "Previous work from our lab and others showed that all ccRCC is characterized by enhanced glycolysis to maintain homeostasis of energy metabolism and anabolic metabolism and association with tumor metastasis, but mutation of the VHL gene was only observed in 35% of our ccRCC patient group." (PMID 27741516, 2016). "Regarding there classification all identified differentially secreted proteins are involved in multiple tumor-associated biological functions and the regulation in the 786-0VHL+ conditioned media coincides with the reduced aggressiveness in the presence of VHL protein." (PMID 26486078, 2015). "VHL-deficient tumor cells have hemangioblastic differentiation capacity." (PMID 26394686, 2015). "Specifically, Clusters C1A and C1B, comprising SDHx- and VHL-mutated tumours, respectively, display a pseudohypoxic signature, whereas Cluster C2A, corresponding to RET-, NF1- and TMEM127-mutated tumours, displays activation of the RAS/mitogen-activated protein kinase (MAPK) signaling pathway." (PMID 25625332, 2015). "The most striking of these is mutation of the von Hippel-Lindau tumor (VHL) suppressor." (PMID 24491179, 2014). "However, clinical correlations and experimental investigations have indicated similarities of EPAS1 lesions to SDHx and VHL mutated tumours." (PMID 24466223, 2014). "We confirmed a germline VHL mutation, as well as loss of 3p and gain of 5q in both tumor regions." (PMID 25159823, 2014). "We propose that in this patient, the development of independent primary kidney cancers in the context of a germline VHL mutation occurs by a different sequence of genomic abnormalities in each tumor, contingent upon the nature of a chromosome 3p LOH event occurring early in tumorigenesis." (PMID 25159823, 2014). "In fact, the inhibition of autophagy by MiR-204 suppressed the tumor growth in VHL-deficient cells." (PMID 24763318, 2014). "Through the analysis of spatially and temporally separate ccRCC tumors from a young patient with germline VHL mutation, these data highlight the complementary properties of contingency and convergence during tumor evolution within an identical genetic background and tissue microenvironment." (PMID 25159823, 2014). "Loss of heterozygosity could be detected in tumour DNA from 11/12 patients having somatic or germline mutations in the SDHB or VHL genes." (PMID 24466223, 2014). "Thus, the molecular pathway for tumor growth in FH deficiencies closely resembles VHL deficiency in clear RCCs." (PMID 24684806, 2014). "The VHL (Von Hippel-Lindau) gene, located on chromosome 3p25, is strongly associated with the development of a dominantly inherited cancer syndrome predisposing to a variety of neoplasms." (PMID 25490036, 2014).
tumor (continued). "HIF-1α is highly expressed in human cancers as a result of intratumoral hypoxia as well as genetic alterations, such as gain-of-function mutations in oncogenes (for example, ERBB2) and loss-of-function mutations in tumour-suppressor genes (for example, VHL and PTEN)." (PMID 23382894, 2013). "Additionally, VHL copy number and mutation analyses were performed on DNA from cryo-preserved tumor tissues of 20 ccRCC patients." (PMID 24086736, 2013). "As expected, missense or truncating VHL mutations were observed in 73% of the tumours." (PMID 23606570, 2013). "Interestingly, cells derived from many established cancers show elevated levels of autophagy, and multiple oncogenes and tumor suppressors (such as VHL) encode enzymes of the UPS involved in ubiquitin conjugation or deconjugation." (PMID 23800266, 2013). "Importantly, FLCN protein levels are diminished in human ccRCC with VHL loss, further supporting a role for this tumor suppressor in the growth of ccRCC." (PMID 23922894, 2013). "Moreover, clear-cell RCC is frequently associated with the loss of von Hippel-Lindau (VHL) tumour suppressor gene function, which results in the aberrant transcriptional activation of genes that contribute to tumour growth and metastasis." (PMID 22937740, 2012). "It was also recently suggested that HIF1α may function as a tumor suppressor gene in VHL-deficient clear cell kidney cancer." (PMID 23178531, 2012). "Thus, RCC with loss of VHL is a highly vascularized and treatment-resistant tumor and is one of the most studied tumors treated with anti-angiogenic therapy." (PMID 22965141, 2012). "This is a significant finding as it implies that HDAC inhibitors may have a therapeutic effect in VHL deficient tumours (such a renal cell cancer and pancreatic neuroendocrine tumours)." (PMID 22414300, 2011). "In addition, statistically significant associations between VHL promoter hypermethylation and low fruit intake frequency were observed, particularly in tumor DNA from smokers." (PMID 22022277, 2011). "Therefore, this analysis relied upon few cases that were both heterozygous/homozygous for the VHL germline variants which also had promoter hypermethylation in tumor tissue." (PMID 22022277, 2011). "Indeed, it has been demonstrated that gain-of-function mutations in oncogenes such as HER2 or EGFR and loss-of-function mutations in tumor-suppressor genes such as VHL or PTEN induce HIF-1 activity." (PMID 21966417, 2011). "Hence, we conclude that despite the common activation of HIF pathways in VHL- and FH-associated neoplasia, the oncogenic mechanisms are likely to be different." (PMID 22014577, 2011). "This recommendation was based on literature reports that have calculated that patients with an apparently isolated VHL-related tumor and no detectable VHL mutation have a risk of ≈ 5% of developing subsequent VHL-related tumors within 10 years of the diagnosis of their first tumor." (PMID 20064270, 2010). "We describe the uptake of diagnostic and presymptomatic genetic testing in a series of 109 individuals for VHL disease, the results of the initial screening for VHL-related tumors in mutation-carriers, and the uptake and subsequent adherence to tumor surveillance over a five year period." (PMID 20064270, 2010). "Thus, under hypoxic stress, inactivation or loss of VHL function appears to be an early and requisite step in tumor development." (PMID 20300531, 2010). "Therefore, we aimed this prospective study for evaluating the association between VHL status (mutation, deletion, promoter methylation and pVHL expression), tumour VEGF expression, plasma VEGF levels and usual prognostic parameters in CCRCC." (PMID 19755989, 2009). "Decreased expression of the adherens junction protein, E-cadherin, following VHL loss may further break down cell-cell adhesion, aiding in tumor formation." (PMID 19602254, 2009).
tumor (continued). "Thus, papillary RCCs demonstrated a geometric mean of 62.5 tumour-specific methylated CpGs per tumour, sporadic cRCCs had a geometric mean of 25.5 and VHL-associated cRCCs 20.9 methylated CpGs per tumour." (PMID 19493342, 2009). "Its haploinsufficiency may facilitate the development of CC-RCC in association with VHL mutations, or otherwise lead to increased risk for other types of tumor." (PMID 19642973, 2009). "Haploinsufficiency of TRC8 may facilitate development of clear cell-RCC in association with VHL mutations, and may increase risk for other tumor types." (PMID 19642973, 2009). "Similarly, tumours presenting biallelic inactivation of the VHL gene were associated with decreased VEGF tumour expression (P=0.0001) and plasma VEGF levels (P=0.005)." (PMID 19755989, 2009). "Additionally, out of the 68 tumours with two or three VHL alterations, which potentially alter both alleles of the gene, 33 (48.5%) exhibited low VEGF tumour expression, and out of the 34 remaining tumours, 25 (73.5%) had high VEGF tissue expression." (PMID 19755989, 2009). "Thus the combination of the two alleles associated with increased tumour risk in VHL patients was also associated with the highest risk." (PMID 19551141, 2009). "Inactivation of the remaining wild-type VHL allele in a susceptible cell leads to tumor formation." (PMID 18773095, 2008). "However, several lines of evidence suggest that dose-dependent effects on basal HIF levels influence VHL-associated tumor development and behavior." (PMID 19030229, 2008). "Genetically, VHL is causedby germline mutations in the VHL tumor suppressor gene located on 3p25-26 accompanied by inactivation of thewild-type copy of the VHL gene in asusceptible cell through loss of heterozygosity (LOH), promoterhypermethylation, or somatic mutation." (PMID 19009041, 2008). "VHL has been linked to a number of phenotypes at the cellular level that may be important for tumor suppression." (PMID 17598890, 2007). "In most VHL-disease related tumours, this "loss of heterozygosity" has been demonstrated." (PMID 17922902, 2007). "Thus, among the 48 clear cell RCC tumours analyzed in the present study, at least 20 samples would be expected to carry a VHL mutation compared to 4 mutations detected here." (PMID 17997830, 2007). "Individuals who inherit one defective copy of the VHL gene have a substantial risk for developing a variety of neoplasias, and in these patients the specific type of VHL mutation (e.g., types of missense, frameshift, deletion, etc) can influence the risk and type of tumour development." (PMID 16465192, 2006). "Subsequent somatic VHL gene deletion and mutation in selected C cells may lead to further transformation and tumor progression." (PMID 16707008, 2006). "VHL gene mutations leading to reduced or inactive VHL protein (pVHL) could theoretically lead to a larger tumor size." (PMID 15932632, 2005). "Our results, derived from the analysis of the largest available cohort with VHL germline mutations (to our knowledge), reveal previously unknown mutation- and organ-specific differences in tumor penetrance, number of organs affected, number of surgeries and outcome." (PMID 40202835, 2025). "Thus, the restoration of VHL renders RCC tumor cells more susceptible to NK cell-mediated killing." (PMID 40736709, 2025). "Finally, a single VHL-component tumor could be attributed to age-related penetrance or the low penetrance of certain VHL alleles in adults." (PMID 40647474, 2025). "Indeed, in a retrospective analysis of 184 patients presenting VHL-associated and sporadic HBLs, the median growth rate of tumors was increased from 1.6 mm3/month to 82.4 mm3/month once a cystic component appeared in the tumor." (PMID 39057165, 2024).
tumor (continued). "Another set of criteria, developed through the use of the Danish vHL database, suggests that a diagnosis may be made if a patient displays any two vHL-associated tumors or if a patient displays one vHL-associated tumor and has at least one first-degree relative with a vHL diagnosis." (PMID 39678829, 2024). "However, some VHL–/– ccRCC lines are not affected by manipulations of HIF2α activity, and some VHL-mutant ccRCCs were resistant to HIF2α inhibitor treatment, suggesting that deficiency of VHL promotes tumor development by yet unidentified and HIF2α-independent mechanisms." (PMID 38360997, 2024). "Therefore, a VHL-deficient mutant may reprogram the tumor immune landscape, offering insights into potential therapeutic strategies for ccRCC." (PMID 39451551, 2024). "To evaluate whether VHL-associated ccRCC tumor-specific exosomal miRNA could be detected, we initially compared the 15 preoperative urine samples to the 28 postoperative urine samples, assuming that the surgical excision of the ccRCC tumor would result in differential expression." (PMID 39062684, 2024). "However, from the tumor size of the patients, we might suggest that the detected type of VHL mutations can positively influence the growth of the tumor." (PMID 37445575, 2023). "However, several patients may develop HBLs known as VHL syndrome (OMIM #193300) due to germline inactivating mutations in the VHL tumor suppressor gene (NM_000551.3, 3p25-26), which exhibits an autosomal dominant inheritance pattern." (PMID 37273678, 2023). "Interestingly, VHL is expressed minimally in platelets, which may allow for tumor-selective degradation of targets classically associated with producing thrombocytopenia when inhibited." (PMID 36991452, 2023). "However, also a relevant proportion of cells with uncertain malignant features were found to carry the same VHL mutation that was found blindly in the tumor tissue, showing that the presence of incomplete malignant features does not exclude the tumor cell nature." (PMID 37444476, 2023). "Consistently with Knudson’s two-hit hypothesis, the first transformed cell of the tumor appears only after the wild-type VHL allele is also inactivated in a cell through a somatic mutation, resulting in the formation of a clonal neoplastic cell that can develop into a tumor mass." (PMID 36611440, 2023). "In VHL disease, tumor susceptibility is underlain by genetic abnormalities behaving as tumor suppressor genes, causing a dysfunctional VHL-Hypoxia Inducible Factor (HIF) pathway, according to the 2-hit hypothesis for the development of cancer and Knudson’s theory of human carcinogenesis." (PMID 36358771, 2022). "We could see that the top 5 keywords listed were gene-mutations, complex-II gene, diagnosis, MIBG, and VHL (different keywords representing the same meaning were treated as the same keyword, such as tumor and tumors, gene-mutations and germline mutations, and multiple endocrine neoplasms and MEN)." (PMID 36185194, 2022). "Interestingly, mutated VHL reduced the expression of HLA class I antigens that might protect tumor cells from T cell recognition, but renders them more susceptible to NK cell cytotoxicity." (PMID 35663987, 2022). "An interesting observation was about a frameshift mutation, c.270dupC, in VHL in patient P11, where allele frequency of this mutation was much higher in both liquid biopsy fractions compared to that of tumor DNA (3%, 20%, and 21.5% in tumor, cfDNA, and evDNA, respectively." (PMID 34830979, 2021). "Moreover, IHC staining using clinical RCC tissues demonstrated that, whereas HIF-1α was expressed in entire tumor tissue including the proximal regions of tumor vessels due to the loss of VHL, SPINK1 expression was predominantly detected in perinecrotic regions distal to blood vessels." (PMID 34747365, 2021).